FMR1 (fragile X messenger ribonucleoprotein 1)
Diseases named in the same sentence as FMR1 in open-access papers (continued):
Sharing a sentence is not in itself a finding about the gene and the disease.
fragile X syndrome (continued). "Background/Objectives: Fragile X Syndrome (FXS) is a neurodevelopmental disorder caused by a triplet repeat expansion in the Fmr1 gene leading to the loss of Fragile X Messenger Ribonucleoprotein (Fmr1 protein)." (PMID 42041789, 2026). "The emerging number of ncRNAs associated with intellectual disabilities have offered valuable insights into the potential role of lncRNAs in genetic disorders caused by abnormal DNA methylation, such as the FMR1 gene in Fragile X Syndrome (FXS)." (PMID 40149464, 2025). "Mutations in the FMR1 gene lead to one of the most common single‐gene causes of intellectual disability and autism, fragile X syndrome (FXS)." (PMID 39928301, 2025). "Fragile X syndrome (FXS) is an X-linked neurodevelopmental disorder caused by loss of function of FMR1, and females are expected to have milder neurodevelopmental presentations than males." (PMID 40206130, 2025). "The approach was applied to Fragile X syndrome (FXS), a genetic disorder caused by mutations in the FMR1 gene." (PMID 39942646, 2025). "Fragile X syndrome (FXS) is a genetic disorder caused by transcriptional silencing of the FMR1 gene on chromosome X." (PMID 40969341, 2025). "Fragile X syndrome (FXS) stems from an FMR1 full mutation or loss-of-function variant, typically causing developmental delay, intellectual disability, and behavioral challenges in affected males." (PMID 40291849, 2025). "The genetic pathway of Fragile X Syndrome (FXS) is centered on mutations in the FMR1 gene located on the X chromosome." (PMID 40728973, 2025). "Concerning ASD, Fragile X Syndrome (FXS) is another intellectual developmental disorder characterized by mutations in mitochondrial genes, including FMR1, which presents with neurodevelopmental and psychiatric challenges." (PMID 40867184, 2025). "Fragile X syndrome (FXS) is a neurodevelopmental disorder resulting from an X‐linked mutation in FMR1." (PMID 41207793, 2025). "Fragile X syndrome (FXS), the most common inherited form of intellectual disability, is caused by mutations or epigenetic changes that disrupt fragile X messenger ribonucleoprotein 1 (FMR1), an X-linked gene essential for normal neurodevelopment." (PMID 40588021, 2025). "FMR1 was originally recognized for its association with the neurodevelopmental disorder fragile X syndrome (FXS) and has traditionally been studied in the context of the central nervous system." (PMID 41184982, 2025). "Fragile X syndrome (FXS) is a neurodevelopmental disorder caused by the expansion of a CGG repeat in the 5’UTR of the FMR1 (fragile X messenger ribonucleoprotein 1) gene." (PMID 40287634, 2025). "In addition to environmental ASD models, we also performed the same neurochemical analysis in adolescent rats with a genetic deletion of Fragile X messenger ribonucleoprotein 1 (Fmr1) (Fmr1‐Δexon 8 rats), which causes Fragile X Syndrome, the most common inherited form of ASD." (PMID 40437860, 2025). "Evidence suggests that carriers of FMR1 mutations (e.g., fragile X syndrome and the FMR1 premutation) may demonstrate specific phenotypic patterns shared with autism (AU), particularly in the domain of pragmatic language, which involves the use of language in social contexts." (PMID 40141125, 2025). "Moreover, syndromic POI may also be caused by the expansion of a CGG repeat in the 5’ regulatory region of the FMR1 gene, which causes Fragile-X syndrome." (PMID 38649916, 2024). "Fragile X syndrome (FXS) is caused by the full mutation in the FMR1 gene on the Xq27.3 chromosome region." (PMID 39063191, 2024). "The fourth cluster is a small, concentrated cluster on fragile X syndrome (FXS) caused due to modifications in the FMRP gene (“54_fxs_fragile_fmrp_fmr1”)." (PMID 39600653, 2024). "Fragile X Syndrome (FXS) is a rare genetic syndrome caused by the expansion of the CGG repeat in the 5’ untranslated region of the FMR1 (Fragile X Messenger Ribonucleoprotein 1) gene located on the X chromosome." (PMID 38997701, 2024).
fragile X syndrome (continued). "It is linked to a genetic premutation in the FMR1 gene on the X chromosome, which is also associated with fragile X syndrome (FXS)." (PMID 39501809, 2024). "Fragile X syndrome (FXS) is a genetic condition caused by the inheritance of alleles with >200 CGG repeats in the 5′ UTR of the fragile X messenger ribonucleoprotein 1 (FMR1) gene." (PMID 39769443, 2024). "Fragile X syndrome (FXS) is a rare neurodevelopmental disorder caused by a CGG repeat expansion ≥ 200 repeats in 5' untranslated region of the FMR1 gene, leading to intellectual disability and cognitive difficulties, including in the domain of communication." (PMID 38946987, 2024). "Fragile X syndrome (FXS) is a rare neurodevelopmental disorder caused by a repeat expansion of > 200 CGG repeats in the 5’ untranslated region of the FMR1 gene located on the X chromosome." (PMID 39488698, 2024). "To fill this major gap, we compared the development of auditory temporal processing in male and female wildtype (WT) and Fmr1 knock-out (KO) mice, a model of Fragile X Syndrome (FXS), a leading genetic cause of ASD-associated behaviors." (PMID 38720271, 2024). "We investigated early life communicative and cognitive abilities in a mouse model of Fragile X Syndrome (FXS), a prominent genetic cause of autism spectrum disorder resulting from a mutation in the Fmr1 gene on the X-chromosome." (PMID 38383408, 2024). "Fragile X syndrome (FXS) is a triplet repeat disease caused by the extension of CGG repeats in the fragile X messenger ribonucleoprotein 1 (FMR1) gene, which resides in the 5′ end noncoding region on the X chromosome." (PMID 38752176, 2024). "Finally, FMR1 (−0.501-fold), whose gene mutation is typically associated with Fragile X syndrome, was found to be highly expressed in the brain and may have a function in germ cell proliferation." (PMID 39335533, 2024). "For example, FMR1 is associated with the Fragile X syndrome (FXS) and has been reported to regulate protein translation through binding to the coding regions without consensus sequence preferences." (PMID 37280234, 2023). "Fragile X syndrome (FXS) is caused by a repression of the FMR1 gene that codes the Fragile X mental retardation protein (FMRP), an RNA binding protein involved in processes that are crucial for proper brain development." (PMID 37834379, 2023). "This study characterizes the DNA methylation patterns specific to fragile X syndrome (FXS) with a full mutation (FM > 200 CGGs), premutation (PM 55–199 CGGs), and X inactivation in blood and brain tissues at the 3′ boundary of the FMR1 promoter." (PMID 37445892, 2023). "Fragile X syndrome (FXS) is the most common consequence of genetic intellectual disability caused by the CGG/CCG tandem repeat sequences of Fragile X Messenger Ribonucleoprotein 1 (FMR1) on the X chromosome." (PMID 37021044, 2023). "Fragile X syndrome (FXS) is an X-linked triplet repeat expansion disorder caused by the unstable expansion of CGG repeats in the 5′untranslated region of the FMR1 gene." (PMID 36979972, 2023). "Fragile X syndrome (FXS) is an inherited human mental retardation that arises from expansion of a CGG repeat in the Fmr1 gene, causing loss of the fragile X mental retardation protein (FMRP)." (PMID 37453994, 2023). "Fragile X syndrome (FXS), resulting from a mutation in the Fmr1 gene, is the most common monogenic cause of autism and inherited intellectual disability." (PMID 37323585, 2023). "An expansion of a CGG trinucleotide repeat in the 5′ UTR of the Fragile X Messenger Ribonucleoprotein 1 (FMR1) gene on the X chromosome is the cause of Fragile X Syndrome (FXS)." (PMID 37628570, 2023). "Fragile X syndrome (FXS) is an X-linked dominant disorder caused by the low expression of the FMR1 gene due to excessive CGG repeats in its 5′ untranslated region." (PMID 37222855, 2023).
fragile X syndrome (continued). "Fragile X syndrome (FXS)—the most common inherited form of intellectual disability and autism—is caused by transcriptional silencing of the fragile X mental retardation 1 (FMR1) gene, coding for the fragile X syndrome retardation protein (FMRP)." (PMID 37371058, 2023). "FXTAS and fragile X syndrome (FXS) are both associated with a CGG trinucleotide repeat expansion on the FMR1 gene located on the X chromosome." (PMID 35401394, 2022). "In addition, the loss or malformation of spines is frequently associated with various psychiatric disorders, including schizophrenia, and autism spectrum disorder, including fragile X syndrome (FXS) caused by the mutation in the fragile X mental retardation 1 (FMR1) gene." (PMID 36301793, 2022). "Fragile X syndrome (FXS), the most common form of inherited intellectual disability, is caused by a developmentally regulated silencing of the FMR1 gene, but its effect on human neuronal network development and function is not fully understood." (PMID 35216162, 2022). "For instance, Fragile X Syndrome (FXS) is the most common genetic cause of autism caused by a single gene mutation of the fragile X mental retardation gene 1 (Fmr1) encoding the fragile X mental retardation protein (FMRP)." (PMID 35530178, 2022). "In addition, both FXR1 and FMR1 are mutated in the R-loop associated disease, Fragile X syndrome." (PMID 35666183, 2022). "Fragile X syndrome (FXS) is a global neurodevelopmental disorder caused by the expansion of CGG trinucleotide repeats (≥200) in the Fragile X Messenger Ribonucleoprotein 1 (FMR1) gene." (PMID 36672829, 2022). "As one of the most frequent inherited reasons for intellectual disability (ID), fragile X syndrome (FXS) is caused by silencing of the fragile X gene FMR1 due to large expansions of non-coding CGG repeats." (PMID 35205326, 2022). "Fragile X syndrome (FXS) is caused by a mutation in the FMR1 gene which can lead to a loss or shortage of the FMR1 protein." (PMID 35322102, 2022). "Fragile X syndrome (FXS) is a genetic disorder caused by mutations in the FMR1 (fragile X mental retardation 1) gene." (PMID 34791268, 2022). "Fragile X syndrome (FXS) is caused by an abnormal expansion of the number of trinucleotide CGG repeats located in the 5' UTR in the first exon of the FMR1 gene." (PMID 36140775, 2022). "Specifically, in the mouse model for fragile X syndrome (FXS), a disorder caused by a mutation of the gene that codes for the FMR1 protein, profound deficits are observed in social interaction and in the organization of the somatosensory cortex." (PMID 35840800, 2022). "Fragile X syndrome (FXS) is caused by loss of function of the fragile X messenger ribonucleoprotein (FMRP), which is typically caused by epigenetic silencing of the FMR1 gene due to an expanded CGG repeat in the promoter." (PMID 36547476, 2022). "Furthermore, this miRNA family has been shown to regulate FMR1 gene expression—a gene vital for dendritic spine and synapse development, and loss of function of which results in the debilitating neuropsychiatric disorder Fragile X syndrome." (PMID 36217923, 2022). "The R138Q mutation in the Fragile X Mental Retardation 1 (FMR1) gene has been associated with Fragile X syndrome (FXS)." (PMID 33692361, 2021). "Here, we show that Fmr1, whose loss-of-function leads to Fragile X Syndrome (FXS), cell autonomously promotes maturation of callosal excitatory synapses between somatosensory barrel cortices in mice." (PMID 34617509, 2021). "In such cases, FMR1 is silenced due to complete CpG methylation of its promoter domain, finally causing fragile X syndrome (FXS; OMIM #300624)." (PMID 34501340, 2021). "Fragile X syndrome (FXS) is caused by silencing of the human FMR1 gene and is the leading monogenic cause of intellectual disability and autism." (PMID 34658956, 2021). "Fragile X Syndrome (FXS) is a neurodevelopmental disorder caused by silencing of the Fragile X Mental Retardation (FMR1) gene." (PMID 34354107, 2021).
fragile X syndrome (continued). "CGG repeat expansions of more than 200 trinucleotide repeats, located at the 5’UTR end of fragile X mental retardation gene 1 (FMR1) causes a neurodevelopmental disorder called the fragile X syndrome (FXS)." (PMID 34638292, 2021). "In a different study CGG repeats were successfully removed from the FMR1 gene in iPSCs with the fragile X syndrome (FXS) mutation." (PMID 33921346, 2021). "Fragile X syndrome (FXS) is a disease associated with abnormal expansion of more than 200 CGG repeats in the FMR1 gene." (PMID 33644055, 2021). "Fragile X syndrome (FXS) is a result of loss of expression of the Fragile X syndrome mental retardation 1 (FMR1) gene most commonly through expansion of a CGG triplicate repeat located in the 5′ untranslated region." (PMID 33262688, 2020). "We also found that 74.6% FXTAS patients had family history of FMR1 gene associated diseases including Fragile X syndrome (FXS), FXTAS or fragile X-associated primary ovarian insufficiency (FXPOI)." (PMID 32312236, 2020). "One such synaptic protein is fragile-X mental retardation protein (FMRP), encoded by the FMR1 gene (Xq27.3) and the monogenic cause of neurodevelopmental disorder fragile X syndrome (FXS)." (PMID 34883502, 2020). "Fragile X syndrome (FXS) is a rare genetic condition caused by cytosine-guanine-guanine (CGG) repeat expansion in the FMR1 gene located on the X chromosome." (PMID 31370779, 2019). "Fragile X syndrome (FXS) is a genetic disorder caused by a mutation in the Fragile X mental retardation 1 (FMR1) gene." (PMID 31652302, 2019). "Loss of FMRP function, due to an expansion repeat in the FMR1 gene on the long arm of the X chromosome, is a cause of fragile X syndrome (FXS), the most common monogenic form of inherited intellectual disability." (PMID 30583851, 2019). "Fragile X syndrome (FXS) is a genetic disorder caused by a pathological expansion of a triplet repeat in the 5’ untranslated region of the FMR1 gene." (PMID 30717399, 2019). "BK malfunction has been also related to Fragile X syndrome (FXS), a monogenic form of intellectual disability and autism, associated to transcriptional silencing of the Fmr1 gene encoding Fragile X mental retardation protein (FMRP)." (PMID 30104956, 2018). "The fragile X syndrome (FXS) is caused by a CGG repeat expansion at the fragile X mental retardation (FMR1) gene." (PMID 29760651, 2018). "The gene fmr1 is implicated in Fragile X syndrome (FXS) and is associated with clinically relevant behaviours including mental retardation, sleep disorders, hyperactivity, and autistic behaviour." (PMID 30262549, 2018). "Beginning with the discovery in 1991 that fragile X syndrome (FXS) was caused by an expansion of more than 200 CGG repeats in the FMR1 gene, the importance of this gene for brain development and functioning is now well-established." (PMID 29868121, 2018). "Fragile X syndrome (FXS) is the most common cause of inherited mental retardation caused by expansion of a (CGG) repeat region up to 1000 repeat in 5' region of the FMR1 gene located in FRAXA locus Xq27.3." (PMID 29379561, 2018). "Fragile X syndrome (FXS)-the leading inherited cause of ID- is caused by the expansion of a CGG trinucleodide repeat located in the FMR1 gene on the long arm of the X chromosome." (PMID 30327664, 2018). "The positive effect of arbaclofen on social functioning has been demonstrated in rodent studies using a mouse model of the FMR1 gene mutation that causes Fragile X Syndrome (FXS)." (PMID 29797620, 2018). "Fragile X syndrome (FXS) is a genetic disorder due to the silencing of the Fmr1 gene, causing intellectual disability, seizures, hyperactivity, and social anxiety." (PMID 29104533, 2017). "Fragile X syndrome (FXS) is a neurodevelopmental disorder caused by mutations in the FMR1 gene that inactivate expression of the gene product, the fragile X mental retardation 1 protein (FMRP)." (PMID 28894415, 2017).
fragile X syndrome (continued). "Fragile X syndrome (FXS), is caused by a loss-of-function mutation in the FMR1 gene located on the X-chromosome, which leads to the most common cause of inherited intellectual disability in males and the leading single-gene defect associated with autism." (PMID 28955201, 2017). "Fragile X syndrome (FXS) is the main cause of inherited intellectual disability in humans caused by CGG repeat expansion in the 5′ UTR of the FMR1 gene." (PMID 29209628, 2017). "Clinically the FMR1 gene (Xq27.3) is currently primarily associated with the Fragile X syndrome (FXS), characterized by expansion of CGGn in the 5′UTR region to CGGn>200." (PMID 28454580, 2017). "Large expansions of CGG repeats (> 200 repeats) in FMR1, referred to as full mutations, are associated with fragile X syndrome (FXS)." (PMID 28005950, 2016). "Fragile X syndrome (FXS) is the most common form of inherited intellectual disability, resulting from the loss of function of the fragile X mental retardation 1 (FMR1) gene." (PMID 26855684, 2016). "Fragile X syndrome (FXS) is caused by CGG expansion over 200 repeats at the 5′ UTR of the FMR1 gene and subsequent DNA methylation of both the expanded sequence and the CpGs of the promoter region." (PMID 27014370, 2016). "Fragile X syndrome (FXS) is a monogenic form of neurodevelopmental cognitive impairment associated with CGG repeat expansions (dynamic mutations) in the 5′UTR of the FMR1 gene which can be inactivated by epigenetic modifications." (PMID 26703582, 2015). "Individuals with a full mutation often have Fragile X Syndrome (FXS), which is associated with a ~30% chance of developing autism and low levels of the FMR1 protein (FMRP)." (PMID 25698960, 2015). "Loss of function of the FMR1 gene leads to fragile X syndrome (FXS), the most common form of intellectual disability." (PMID 25693964, 2015). "Fragile X syndrome (FXS) is caused by transcriptional silencing of the fmr1 gene resulting in the loss of fragile X mental retardation protein (FMRP) expression." (PMID 26601124, 2015). "The fragile X syndrome (FXS) results from mutation of the FMR1 gene that prevents expression of its gene product, FMRP." (PMID 25348928, 2014). "Fragile X syndrome (FXS) is a single-gene disorder nearly always caused by an unstable mutation in the fragile X mental retardation 1 (FMR1) X-linked gene and results from the expansion of a trinucleotide (CGG) repeat sequence in the 5’UTR of this gene." (PMID 24942544, 2014). "Fragile X syndrome (FXS), caused by a mutation of the FMR1 gene on the X chromosome, is the most common inherited form of intellectual disability and autism spectrum disorders." (PMID 24354947, 2013). "Fragile X syndrome (FXS) is a trinucleotide repeat disorder caused by a CGG repeat expansion in the FMR1 gene on the X chromosome (> 200 repeats in the full mutation, compared with 6–54 repeats in the normal population)." (PMID 24354947, 2013). "The expansion to over 200 CGG repeats in the FMR1 gene is associated with fragile X syndrome [FXS, FRAXA; MIM#300624], the most common form of familial severe XLID." (PMID 23914978, 2013). "Fragile X syndrome (FXS), the most common inherited from of autism and mental impairment, is caused by transcriptional silencing of the Fmr1 gene, resulting in the loss of the RNA-binding protein FMRP." (PMID 22384253, 2012). "Fragile X syndrome (FXS), the most commonly inherited mental retardation and single gene cause of autistic spectrum disorder, occurs when the Fmr1 gene is mutated." (PMID 21314987, 2011).